VCAM1 (vascular cell adhesion molecule 1)
Diseases named in the same sentence as VCAM1 in open-access papers (continued):
Sharing a sentence is not in itself a finding about the gene and the disease.
diabetes (157 papers, 2005 to 2026). "A panel of ICAM‐1, VCAM‐1, and E‐selectin has predicted Type 2 diabetes and vascular complications, suggesting a composite score could aid ischemic stroke risk prediction in diabetes." (PMID 41567175, 2026). "Based on our previous study showing that Vcam-1+ST-HSCs, which are causally involved in the development of diabetic complications, belonged to Lin(-)Sca-1(+)c-kit(+) cells (LSK cells) in the BM12, LSK cells were then isolated to examine the expression patterns of histone deacetylases (HDACs)." (PMID 37311905, 2023). "Hypothesizing that endothelial cells (ECs) could be a potential source of sCAMs, this study investigated whether dysfunctional EC signaling mechanisms during diabetes cause VCAM1 ectodomain shedding." (PMID 37762417, 2023). "Hence, the anti-inflammatory effect of C66 in diabetes-associated renal impairment appears to be the result partially of the suppressed expression of VCAM-1, ICAM-1, and MCP-1 in the renal epithelium." (PMID 36316651, 2022). "VCAM1, a member of the Ig superfamily, encodes a cell surface salivary gland glycoprotein expressed by endothelial cells, whose main function is to participate in cell adhesion and signaling, and possibly in neurodegenerative diseases of diabetes." (PMID 36118693, 2022). "Diabetes is also associated with upregulation of vascular inflammation including the induction of pro-atherogenic mediators in the thoracic aorta, including the adhesion molecule (VCAM-1) and inflammatory markers (TNFα, IL-6, MCP-1, CD11b, and KLF3)." (PMID 35624851, 2022). "Vascular risk factors including hyperglycemia, advanced glycation end products (AGEs), oxidized lipids found in diabetes and obesity can elevate the expressions of VCAM-1 and ICAM-1 and cause inflammation, and inflammation aggravates the progression of cardiovascular disease." (PMID 36558380, 2022). "In concordance with our findings, Song and his colleagues conducted a prospective nested case-control study to examine the associations between plasma levels of VCAM1 and diabetes risk among 82,069 initially healthy women aged 50–79 years from the Women's Health Initiative Observational Study." (PMID 34179515, 2021). "Earlier evidences also show the association between VCAM-1 and diabetic kidney disease and the significant involvement of P-selectin; a marker of platelet activation, which activates procoagulant imbalance in the pathogenesis of diabetic nephropathy among patients with type 2 diabetes mellitus." (PMID 36843591, 2023). "In one of the study the authors found a positive association between air pollution and inflammatory markers as ICAM-1, VCAM-1 and vWF, suggesting that inflammatory mechanisms may explain the increased risk of air pollution-associated cardiovascular events among persons with diabetes." (PMID 24886318, 2014). "In diabetes, endothelial cells express higher levels of VCAM‐1 due to stimuli like hyperglycemia, TNF‐α, and AGE accumulation." (PMID 41567175, 2026). "In summary, endothelial dysfunction markers such as ET‐1, VCAM‐1, and ADMA provide both mechanistic and clinical relevance for stroke risk prediction in diabetes." (PMID 41567175, 2026). "In metabolic disorder-associated ED, such as that linked to diabetes and obesity, elevated circulating inflammatory cytokines, chemokines (e.g., IL-1), and adhesion molecules (ICAM-1, VCAM-1, and P-selectin) play pivotal roles in disease progression." (PMID 41281764, 2025). "In this study, we demonstrated that diabetes, LDL-C, and elevated serum IL-6 levels serve as independent predictors of CMVO, and that thrombus expression of sCD40-L, hs-CRP, and VCAM-1 is closely associated with microvascular obstruction." (PMID 40988197, 2025).
diabetes (continued). "In diabetes, endothelial cells exhibit an increased expression of adhesion molecules such as vascular cell adhesion molecule-1 (VCAM-1), facilitating monocyte adhesion and migration into the intima." (PMID 40149704, 2025). "MSCs treatment attenuated the expression of ICAM1 and VCAM1 in the aortic endothelium, which was enhanced by diabetes;however, the anti-inflammatory phenotype of MSCs was abolished when STC1 was knocked down." (PMID 41249792, 2025). "Simple logistic regression analyses showed that HIV seropositivity, diabetes mellitus, older age, CVD risk, and Factors 2 (sTNFRII and VCAM-1) and 4 (MMP-2) were significantly associated with DSP (ps < 0.05)." (PMID 38673830, 2024). "Hyperglycemia and oxidative stress in diabetes upregulate VCAM-1 expression, facilitating leukocyte adhesion to the endothelium and amplifying inflammation." (PMID 39727989, 2024). "Downregulation of VCAM1 in prediabetes was surprising because VCAM1, an intercellular adhesion molecule, was previously reported to increase in diabetes due to its role in renal and other diabetic-driven complications." (PMID 39589852, 2024). "Diabetes, an HF risk factor, includes increased inflammation, driven by elevated interleukin (IL-1β, IL-6), intercellular adhesion molecule-1 (ICAM-1), and vascular cell adhesion molecule-1 (VCAM-1), and decreased activity of the collagen-degrading MMP." (PMID 37900404, 2023). "LP-ACE2 treatment repaired BRB dysfunction and reduced diabetes-induced retinal inflammation, as observed by increased ZO-1 expression and reduced VCAM-1 expression and the reduced generation of acellular capillaries." (PMID 36902558, 2023). "There was a simultaneous lowering of VCAM-1 and total adiponectin with increase in vitamin C levels in the blood of subjects with diabetes." (PMID 36235544, 2022). "We found that VCAM1 can inhibit endothelial cell growth and energy metabolism, suggesting that VCAM1 can promote the development of neurodegenerative diseases of diabetes." (PMID 36118693, 2022). "Among patients with diabetes, AGE-RAGE complexes cause a higher production of VCAM-1 (vascular cell adhesion molecule 1), ICAM-1 (intercellular cell adhesion molecule-1), pro-inflammatory interleukins and growth factors." (PMID 36235635, 2022). "Increased VCAM-1 was demonstrated in the serum and plasma of patients with PD, and in the CSF of diabetes patients." (PMID 36247752, 2022). "Diet-induced obesity and diabetes alike enhance the expression of endothelial transmembrane proteins in the heart, such as VCAM-1 and ICAM-1, which facilitate leucocyte adhesion to the vascular wall and endothelial transmigration." (PMID 34671656, 2021). "Models that adjusted only for age and for diabetes plus age had less support based on ∆AICC with the latter model also having a weaker association between U-mining status and VCAM-1." (PMID 34833099, 2021). "Other than that, chronic inflammation in patients with diabetes mellitus demonstrated increased circulating vascular cell adhesion molecule-1 (VCAM-1) and intracellular adhesion molecule-1 (ICAM-1)." (PMID 32456230, 2020). "Strong evidence has been established for the association of higher levels of VCAM‐1 with a higher risk of PAD in patients with hemodialysis and those with diabetes." (PMID 30535754, 2019). "In order to evaluate the potential anti-inflammatory properties and effect on glial cell reactivity, VEGF-α, GFAP, and VCAM-1 mRNA levels were analyzed by FQ-PCR after 42-d treatment (72 d of total duration of diabetes)." (PMID 31396288, 2019). "In a logistic regression analysis, VCAM-1 was robustly associated with the diagnosis of PAD, even after correction for clinically relevant cofounders (namely age, arterial hypertension, diabetes and LDL levels)." (PMID 30535754, 2019).
diabetes (continued). "Even after correction for clinically relevant cofounders (namely arterial hypertension, type 2 diabetes mellitus, age, LDL levels and cigarette smoking), VCAM-1 was still robustly associated with diagnosis of PAD in a logistic regression." (PMID 30535754, 2019). "In a multiple linear regression model, kidney function, IMT, pack-years of smoking, diabetes and level of VCAM-1 were independent predictors of lower FMD%." (PMID 29850964, 2018). "Clarke (2016) identified 12 dietary AGE intervention studies with 293 participants and reported that a high AGE intake increased TNF-α in all populations and increased 8-isoprostanes in healthy subjects and VCAM-1 in people with diabetes." (PMID 29232895, 2017). "We found that diabetes significantly increases VCAM-1 and CD45-positive leukocyte infiltration into the retina compared to normal control rats’ retina." (PMID 27225425, 2016). "A high AGE diet increased 8-isoprostanes in healthy adults, and vascular cell adhesion molecule-1 (VCAM-1) in patients with diabetes." (PMID 26938557, 2016). "One of the human adhesion molecules, vascular cell adhesion molecule-1 (VCAM-1), which facilitates the adherence of mononuclear cells to endothelium, was upregulated upon cardiac risk factors such as hypertension and diabetes." (PMID 26610475, 2015). "In diabetes, macrophages are recruited to sites of vascular injury and roll along the vascular endothelium where VCAM-1 plays a crucial role in priming vascular inflammation." (PMID 25961566, 2015). "Diabetes and hyperglycemia also lead to increased expression of E-selectin, VCAM-1, and ICAM-1 by endothelial cells." (PMID 26539228, 2015). "Eight weeks of streptozotocin-induced diabetes resulted in increased VCAM-1 in wt mice, predominantly in small vessels (<10 μm)." (PMID 20856927, 2010). "Accordingly, the first aim of the present study was to evaluate potential changes in VCAM-1 expression in a streptozotocin (STZ) model of diabetes in mouse." (PMID 20856927, 2010). "To determine the effect of diabetes on endothelial activation in retinal arteries, we measured VCAM-1 expression by confocal immunofluorescence microscopy." (PMID 20856927, 2010). "Results also suggest a complex role for TNFα in the regulation of VCAM-1 expression, being protective under basal conditions but pro-inflammatory in response to diabetes." (PMID 20856927, 2010). "Results also suggest a complex role for TNFα in the regulation of VCAM-1 expression, being protective under basal conditions but promoting endothelial activation in response to diabetes." (PMID 20856927, 2010). "Here we investigated the impact of diabetes and dyslipidemia on VCAM-1 expression in mouse retinal vessels, as well as the potential role of tumor necrosis factor-α (TNFα)." (PMID 20856927, 2010). "The present study investigated early retinal endothelial activation in diabetes and/or dyslipidemia by assessment of VCAM-1 expression in mouse retinal vessels, as well as the potential role of TNFα." (PMID 20856927, 2010). "For a more systemic indication of endothelial activation in response to diabetes, we measured soluble VCAM-1 (sVCAM-1) in plasma from wt, ApoE−/− and ApoE−/−/TNFα−/− mice." (PMID 20856927, 2010). "The third aim of the present study was to evaluate the influence of TNFα on endothelial VCAM-1 expression in diabetes and/or dyslipidemia, using TNFα knockout mice." (PMID 20856927, 2010). "Plasma ADMA and VCAM-1 levels were positively correlated (r = 0.37, p = 0.003) in people with diabetes." (PMID 19486510, 2009). "As well, rosiglitazone improves diabetes compensation, significantlyreducing VCAM-1 level, and E-selectin concentrations in patients with diabetes." (PMID 19107216, 2008). "Combined with markers like hs‐CRP or VCAM‐1, ADMA may improve vascular risk stratification in diabetes." (PMID 41567175, 2026).
diabetes (continued). "Accordingly, VCAM‐1 was found to have a moderating role on attention and abstraction functions in diabetes‐related cognitive impairment, with a moderating effect observed only in the abstraction domain when age was added as a covariate to the model (p = 0.040)." (PMID 39829127, 2025). "Accordingly, VCAM‐1 has a moderating role in diabetes‐related cognitive functions at low (B = −0.356, p = 0.0310 for 49.34 ng/mL), medium (B = −0.355, p = 0.003 for 69.28 ng/mL), and high (B = −0.354, p = 0.041 for 89.22 ng/mL) levels of VCAM‐1 values (p < 0.05)." (PMID 39829127, 2025). "However, VCAM‐1 levels were found to have a moderator effect on abstraction in diabetes‐related cognitive impairment." (PMID 39829127, 2025). "This suggests that although VCAM‐1 levels may moderate the impact on abstraction, the effect is not substantial enough to result in clinically significant impairment in patients with diabetes." (PMID 39829127, 2025). "However, considering the moderator effect of VCAM‐1, the impact of diabetes on cognitive functions is found to be significant." (PMID 39829127, 2025). "Furthermore, in diabetes, there is an upregulation of other adhesion molecules on endothelial cells, such as vascular cell adhesion molecule-1 (VCAM-1), intercellular adhesion molecule-1 (ICAM-1), and E-selectin." (PMID 39064844, 2024). "Furthermore, knocking down ARG1 reduced the high expression levels of vascular endothelial adhesion molecules (Icam1, Et-1, and Vcam1) induced by diabetes." (PMID 39235443, 2024). "The inhibition of GSK3β in vitro and in vivo decreased VCAM1 ectodomain shedding and could possibly offer cardioprotection in diabetes." (PMID 37762417, 2023). "Through mechanisms involved in single cell analysis and cell-cell communication, VCAM1 may play an important role in neurodegenerative diseases of diabetes, and quercetin may be an effective drug for precise treatment of neurodegenerative diseases." (PMID 36118693, 2022). "In addition, quercetin suppressed VCAM1 as well as ROS levels and delayed the progression of neurovascular complication of diabetes." (PMID 36118693, 2022). "In the presence of hyperinsulinemia in type 2 diabetes, it activates the MAPK signaling pathway, which in turn activates the expressions VCAM1 and E-selectin and induces the production of ROS, involved in vascular damage in diabetes, including the neurodegenerative diseases." (PMID 36118693, 2022). "In summary, the elevated levels and dysregulated functions of EC_EndMT may play important roles in diabetes development, while Vcam1 may be involved in mediating the functions of EC_EndMT through ligand-receptor interactions." (PMID 36118693, 2022). "This cross-sectional study indicates that U-mining is associated with upregulation of soluble VCAM-1 and VCAM-1 mRNA expression, as measured by the SCIP assay, even after adjusting for individual, confounding covariates such as age, diabetes, HbA1c, or statin usage." (PMID 34833099, 2021). "Moreover, pharmacological blockade of p300/CBP significantly reduced the diabetes-associated inflammatory response in the kidney, as demonstrated by the knock-down effects on MCP-1, TNFα, NOS2, ICAM-1, VCAM-1, and E-selectin transcript levels." (PMID 34572988, 2021). "The overexpression of adhesion molecules (such as ICAM-1, VCAM-1, ninjurin-1) on EC plasma membrane stimulates monocytes adhesion and transmigration into the subendothelial space, contributing to atherosclerosis initiation and progression in diabetes." (PMID 33375461, 2020). "ICAM-1 and/or VCAM-1 have a good correlation with cardiovascular disease in patients with diabetes." (PMID 32509150, 2020). "There were several studies have described the increased levels of circulating soluble E-selectin in patients with diabetes, obesity, and coronary artery disease, and soluble VCAM-1 and/or soluble ICAM-1 are increased in patients with metabolic syndrome who involve both male and female." (PMID 31550292, 2019).
diabetes (continued). "Serum levels of the cellular adhesion molecule VCAM-1 were significantly associated with hemochromatosis arthropathy, independent of diabetes, BMI, and age." (PMID 28331855, 2017). "Elevated VCAM-1 is also a significant predictor of incident diabetes." (PMID 28331855, 2017). "Real-time PCR (RT-PCR) revealed that STZ-induced diabetes was associated with significantly up-regulated MCP-1 (Mcp1), CSF-1 (Csf1), ICAM-1 (Icam1), and VCAM-1 (Vcam1) expression in Nrf2+/+ and Nrf2−/− mice, and these changes in expression were reversed by digitoflavone in Nrf2+/+ mice only." (PMID 26205695, 2015). "Indeed, the anti-VLA-4α antibody natalizumab was previously shown to impede the interaction of pathogenic T cells with VCAM-1 on endothelial cells, and to prevent the development of EAE and diabetes in mice." (PMID 25522369, 2014). "Before its potential role in DR was examined, it first came to light that VCAM-1 had been involved in the macrovascular complications of diabetes; however, it has since been revealed that the interaction of VCAM-1 with its ligand, integrin VLA-4, is important in the development of DR." (PMID 22132315, 2012). "The fact that the effect of diabetes on VCAM-1 was predominant in small caliber vessels (<10 μm) is interesting considering that capillary degeneration begins early in diabetes retinopathy and as it advances, contributes to the large non-perfused areas of the retina." (PMID 20856927, 2010). "The second aim of our study was thus to assess whether the VCAM-1 expression pattern in retinal vessels was different in dyslipidemic compared to wild type (wt) mouse, and how diabetes would influence such an expression." (PMID 20856927, 2010). "Collectively, it seems that diet-induced VCAM-1 expression may be driven by serum cholesterol, whereas diabetes-induced ICAM-1 expression may be driven by triglycerides in ApoE−/− mice, by a mechanism yet to be described." (PMID 20856927, 2010). "iBRB compromise in diabetic retinopathy is not necessarily separate from theseproinflammatory processes, indeed, during diabetes the retinalmicrovasculature shows enhanced expression of endothelialICAM-1/VCAM-1 adhesion molecules and promotion of capillaryleukostasis." (PMID 17641742, 2007). "Thus, this article highlights the source of sVCAM1 and identifies a potential checkpoint to prevent VCAM1 shedding that could improve cardiovascular function in diabetes." (PMID 37762417, 2023). "Interestingly, both in in vitro and in vivo models of diabetes, the overexpression of endothelial adhesion molecules (ICAM-1, VCAM-1, Selectins), and of the enzymes implicated in their O-GlcNAcylation induced by high glucose levels, were significantly decreased by miR-200a and miR-200b mimics." (PMID 31396056, 2019). "In the present study, the correlation between CSF E-selectin and BMI, as well as the elevation in concentration of CSF VCAM1 in cognitively normal participants with diabetes mellitus, suggests that CSF E-selectin and VCAM1 may be biomarkers for cerebrovascular injuries in the brain." (PMID 28673336, 2017). "In the present study we found that TNFα−/− deficient mice exhibited higher basal levels of VCAM-1 protein in retinal vessels and sVCAM-1 in plasma than wt mice, but these mice failed to up-regulate IL-6 and IL-1β mRNA and VCAM-1 protein in response to diabetes." (PMID 20856927, 2010). "ELISA's findings were consistent with the quantitative RT-PCR results in that the levels of ICAM-1 and VCAM-1 in diabetes rats were much greater than in normal rats, but the treatment of 1,25-D3 reduced the expression levels of ICAM-1 and VCAM-1." (PMID 40224490, 2025). "The intravitreal administration of ADAMTS13 attenuates diabetes-induced BRB breakdown, the downregulation of VE-cadherin and β-catenin, and the upregulation of VWF, CD41, phospho-ERK1/2, HMGB1, VCAM-1, and ICAM-1." (PMID 39851513, 2025).